OR10A4 (olfactory receptor family 10 subfamily A member 4)
Description:
Odorant receptor (Potential). May be involved in taste perception.
Synonyms: OR10A4P; JCG5
Tractability: Antibody: UniProt places it where antibodies can reach, with medium confidence; UniProt predicts a signal peptide or a membrane-spanning region; its Gene Ontology location is reachable by antibodies, with medium confidence.
Gene: Protein-coding gene on chromosome 11 (6,876,625 to 6,877,619, forward strand). Ensembl gene ENSG00000170782.
Subcellular location: Cell membrane
Pathways (Reactome):
Sensory Perception: Expression and translocation of olfactory receptors
Gene Ontology:
Molecular function: olfactory receptor activity; G protein-coupled receptor activity
Biological process: detection of chemical stimulus involved in sensory perception of smell; G protein-coupled receptor signaling pathway
Cellular component: plasma membrane; membrane
Genetic constraint (gnomAD): Loss-of-function variants: 18 observed, 15.86 expected, observed/expected ratio (o/e) 1.13, 90% interval 0.78 to 1.66. The upper end of that interval is the gene's LOEUF score, 1.66, which puts it in group 6 of 6, group 1 being the genes least tolerant of losing a copy. Missense variants: 455 observed, 393.87 expected, observed/expected ratio (o/e) 1.16, 90% interval 1.07 to 1.25. Synonymous variants: 161 observed, 158.34 expected, observed/expected ratio (o/e) 1.02, 90% interval 0.89 to 1.16.
Homologues: Orthologues: macaque OR10A4 (94% identical), rabbit OR10A4 (92% identical), dog OR10A4 (90% identical), mouse Or10a4 (88% identical), rat Or10a4 (87% identical), pig OR10A4 (81% identical). Paralogues in human: OR10A5 (74% identical), OR10A2 (70% identical), OR10A7 (61% identical), OR10C1 (57% identical), OR10A3 (53% identical), OR10A6 (51% identical), OR10P1 (49% identical), OR13C4 (48% identical), OR5V1 (48% identical), OR2S2 (47% identical), OR10AG1 (47% identical), OR13C3 (47% identical), and 80 more.
Diseases named in the same sentence as OR10A4 in open-access papers:
OR10A4 is named in the same sentence as 2 diseases in open-access papers, as found by Europe PMC text mining. Sharing a sentence is not in itself a finding about the gene and the disease.
OR10A4 shares sentences with these, for which no sentence is quoted: cancer (1 paper); tumor (1).